ARRDC2 (arrestin domain containing 2)
Synonyms: PP2703; CLONE24945
Tractability: Antibody: its Gene Ontology location is reachable by antibodies, with high confidence. PROTAC: ubiquitination databases record sites on it.
Gene: Protein-coding gene on chromosome 19 (18,001,126 to 18,014,102, forward strand). Ensembl gene ENSG00000105643.
Subcellular location (Human Protein Atlas): Nucleoplasm
Gene Ontology:
Molecular function: protein binding; molecular adaptor activity
Cellular component: cytoplasmic vesicle; plasma membrane; cytoplasm
Genetic constraint (gnomAD): Loss-of-function variants: 39 observed, 39.26 expected, observed/expected ratio (o/e) 0.99, 90% interval 0.77 to 1.3. The upper end of that interval is the gene's LOEUF score, 1.3, which puts it in group 5 of 6, group 1 being the genes least tolerant of losing a copy. Missense variants: 553 observed, 570.52 expected, observed/expected ratio (o/e) 0.97, 90% interval 0.9 to 1.04. Synonymous variants: 300 observed, 254.55 expected, observed/expected ratio (o/e) 1.18, 90% interval 1.07 to 1.3.
Homologues: Orthologues: chimpanzee ARRDC2 (99% identical), macaque ARRDC2 (94% identical), dog ARRDC2 (92% identical), pig ARRDC2 (91% identical), rat Arrdc2 (83% identical), mouse Arrdc2 (81% identical), guinea pig ARRDC2 (79% identical), zebrafish arrdc2 (60% identical), tropical clawed frog arrdc2 (60% identical), Caenorhabditis elegans arrd-16 (27% identical), Caenorhabditis elegans arrd-7 (22% identical), Caenorhabditis elegans arrd-5 (21% identical), and 8 more. Paralogues in human: ARRDC3 (53% identical), ARRDC4 (46% identical), TXNIP (37% identical), ARRDC1 (26% identical), ARRDC5 (19% identical).
Diseases named in the same sentence as ARRDC2 in open-access papers:
ARRDC2 is named in the same sentence as 9 diseases in open-access papers, as found by Europe PMC text mining. Sharing a sentence is not in itself a finding about the gene and the disease. The quoted sentences say what the papers report.
breast carcinoma (3 papers, 2012 to 2022). "For example, Oncomine analysis of breast cancer data showed that ARRDC2/3/4 and TXNIP appear among the genes most downregulated between normal and cancer tissue, whereas ARRB2 appears among the genes most upregulated." (PMID 23236378, 2012).
ovarian carcinoma (1 paper, 2022). A malignant neoplasm originating from the surface ovarian epithelium. "On the basis of big data analysis, we used PCR and Western blot experiments to verify that the expression level of ARRDC2 in normal ovarian cells (IOSE80) was significantly lower than that in ovarian cancer cells (A2780 and SKOV3)." (PMID 35664304, 2022). "Given that members of the arrestin protein family play a momentous role in the biology of tumors, the function of ARRDC2 in tumors, especially in ovarian cancer, has attracted great interest to us." (PMID 35664304, 2022). "We are the first study to investigate the important role of the ARRDC2 of the arrestin protein family in the occurrence, development and poor prognosis of ovarian cancer." (PMID 35664304, 2022). "The Kaplan-Meier plotter database was used to verify the results of the study that the high expression of ARRDC2 during immune cell infiltration leads to a reduction in the overall survival of patients with ovarian cancer." (PMID 35664304, 2022). "This study brought the role of ARRDC2 as an immune-related prognostic biomarker in ovarian cancer to the public eye for the first time." (PMID 35664304, 2022). "Here, we performed a deep dive into the TCGA database and the GEO database to determine the impact of ARRDC2 on the progression and poor prognosis of ovarian cancer." (PMID 35664304, 2022). "In conclusion, ARRDC2 may affect the malignant progression and poor survival outcomes of patients with ovarian cancer through immunomodulatory effects." (PMID 35664304, 2022). "Therefore, we further explored the relevance of ARRDC2 to immune cells and immune checkpoints in the tumor immune microenvironment of ovarian cancer using the TIMER and TISIDB databases." (PMID 35664304, 2022). "Ovarian cancer tissues showed low levels of ARRDC2 gene methylation." (PMID 35664304, 2022). "From this, it can be boldly speculated that ARRDC2 may likewise act as an oncogene in ovarian cancer and lead to poor prognosis, but its possible oncogenic mechanisms need to be further explored." (PMID 35664304, 2022). "In order to further verify the enrichment of ARRDC2 in the immune-related signaling pathways of ovarian cancer, GSEA was used to analyze the data of two groups of OV patients from the TCGA database (ARRDC2 high expression group and ARRDC2 low expression group)." (PMID 35664304, 2022). "In addition, the TIMER and TISIDB database were used to conduct in-depth research on the role of ARRDC2 in the change of the immune microenvironment of ovarian cancer." (PMID 35664304, 2022). "However, little is known about the significance of ARRDC2 in ovarian cancer." (PMID 35664304, 2022). "Notably, previous studies are highly consistent with our study that ARRDC2 may serve as a new target for immunotherapy and may provide a new direction for subsequent immunopharmacological treatment of ovarian cancer." (PMID 35664304, 2022). "The analysis of a total of 34 normal ovarian tissues and 23 ovarian cancer tissues from two GEO datasets (GSE29450 and GSE10971), revealed that the ARRDC2 expression was high and statistically significant in tumor tissues." (PMID 35664304, 2022). "However, the role of ARRDC2, an important member of this family, in the malignant biological process of ovarian cancer (OC) has not been reported, and its role in the change of the immune microenvironment is also unknown." (PMID 35664304, 2022).
cancer (5 papers, 2012 to 2024). A tumor composed of atypical neoplastic, often pleomorphic cells that invade other tissues. "ARRDC2, ARRDC4, and TXNIP share common association with certain neurodegenerative diseases, while ARRDC1 is implicated in cancer." (PMID 38270169, 2024). "Multivariate Cox analysis showed that the high expression of ARRDC2 (HR = 1.043; 95% CI = 1.022–1.063; p < 0.001), age (HR = 1.435; 95% CI = 1.101–1.870; p = 0.008) and person neoplasm cancer status (HR = 3.117; 95% CI = 2.410–4.032; p < 0.001) were high risk factors." (PMID 35664304, 2022). "ARRDC2 has abnormally high expression in a variety of human malignant tumors." (PMID 35664304, 2022). "The exact function of the other genes in the top rank, FAM174A, ARRDC2, and ARMS2, remained unknown in ATO or cancer research." (PMID 37251921, 2023).
tumor (1 paper, 2022). "In this study, we tried to use a variety of databases to explore and verify the expression level of ARRDC2, the relationship between ARRDC2 and clinical features and prognosis, potential molecular mechanisms and impact on tumor immune microenvironment." (PMID 35664304, 2022). "Excitingly, a close correlation was found between ARRDC2 expression and the tumor immune microenvironment of the tumor including infiltration of immune cells, immune checkpoint and chemokines." (PMID 35664304, 2022). "In conclusion, this study fully confirmed the close correlation between ARRDC2 and important tumor immune microenvironment components such as immune cell infiltration and immune checkpoints." (PMID 35664304, 2022). "In addition, the relationship between ARRDC2 expression and clinical characteristics in 361 tumor samples from TCGA in the UALCAN database was explored." (PMID 35664304, 2022). "In conclusion, DNA methylation of ARRDC2 may be responsible for the difference in ARRDC2 expression levels in normal and tumor tissues." (PMID 35664304, 2022). "However, tumor relevance studies of ARRDC2 have not been reported." (PMID 35664304, 2022).
ARRDC2 also shares sentences with these, for which no sentence is quoted: Crohn disease (1 paper); infection (1); melanoma (1); neurodegenerative disease (1); type 1 diabetes (1).